CRP (C-reactive protein)
Diseases named in the same sentence as CRP in open-access papers (continued):
Sharing a sentence is not in itself a finding about the gene and the disease.
schizophrenia (continued). "Our finding of a positive correlation between CRP and BMI is consistent with the results of previous studies in mentally healthy overweight and obese individuals as well as in schizophrenia patients." (PMID 40980040, 2025). "This association was underscored by a study involving 208 patients with schizophrenia, where a decrease in CRP levels was found to be correlated with overall improvements in global cognitive performance." (PMID 39273641, 2024). "GWAS catalog reported genes enrichment analysis showed that the identified genes are enriched in gene sets related to schizophrenia, serum lipid metabolism (including triglycerides), and C-reactive protein." (PMID 39677857, 2024). "We evaluated 40 patients with schizophrenia, schizoaffective, or bipolar disorder receiving SGAs by oGTT, HbA1c, comprehensive metabolic and lipid panels, and CRP." (PMID 39121088, 2024). "In accordance, Dr Yolken’s team, with over two decades of research on infections and immune dysregulation in schizophrenia, recently published a pilot study discussing the potential value of CRP and C4 complement as informative biomarkers in schizophrenia." (PMID 38389990, 2024). "We identified seven inflammation markers linked to schizophrenia onset, which all passed the Bonferroni correction for multiple comparisons (bNGF, GROA(CXCL1), IL-8, M-CSF, MCP-3 (CCL7), TNF-β, CRP)." (PMID 38445386, 2024). "In both acute and chronic phases of schizophrenia, elevated levels of CRP have been observed, as indicated by a study exploring acute psychosis." (PMID 39273641, 2024). "This study compared the demographic characteristics and serum levels of vitamin D, calcium, phosphorus, PTH, and CRP in three groups of patients, including schizophrenia, bipolar disorder, and methamphetamine-induced psychosis, with a control group." (PMID 37803327, 2023). "It has previously been shown that neutrophils, monocytes, and CRP are in general increased in schizophrenia patients vs. controls at baseline." (PMID 37032951, 2023). "In support of this, several studies have found a relationship between current cognitive function (including IQ) and CRP in schizophrenia." (PMID 35177144, 2023). "Serum CRP levels in patients with schizophrenia, bipolar disorder type 1, and methamphetamine-induced psychotic disorder were significantly higher than in the control group (p < 0.001)." (PMID 37803327, 2023). "A diet rich in fibers is recommended to reduce inflammatory biomarkers, such as C-reactive protein (CRP) and IL-6, which are also involved in neuroinflammatory mechanisms and schizophrenia." (PMID 36946488, 2023). "Third, both increased blood cytokine levels and elevated serum levels of C-reactive protein (CRP) have been reported in patients with schizophrenia." (PMID 36401749, 2023). "For example, cumulative evidence suggests that higher serum levels of CRP protect individuals from developing schizophrenia, even though elevated CRP is correlated with disease activity after onset of schizophrenia." (PMID 36831896, 2023). "There are many studies investigating the relationship between cognitive impairment and CRP in schizophrenia patients." (PMID 37763110, 2023). "The final baseline sample comprised 194 individuals with recent-onset schizophrenia and CRP < 10 mg/L." (PMID 37723153, 2023). "C-reactive protein levels have repeatedly been shown to be altered in patients with schizophrenia as compared to healthy individuals." (PMID 37032951, 2023). "In a naturalistic sample of 82 outpatients diagnosed with schizophrenia, all the inflammatory markers, but in particular suPAR and CRP, were inversely correlated with CRF at baseline." (PMID 37265560, 2023). "In a study, it was reported that CRP levels, which were higher in schizophrenia patients, decreased after treatment, and CRP was recommended as a prognostic marker." (PMID 37763110, 2023).
schizophrenia (continued). "The C-reactive protein (CRP) has been shown to correlate with disease severity and is associated with cognitive function in schizophrenia." (PMID 36979236, 2023). "The significant association between measures of functional impairment and elevated CRP was detected in a group of stable outpatients with schizophrenia." (PMID 35873262, 2022). "In conclusion, the present study found that higher plasma COLA was associated with higher CRP and homocysteine levels, and lower plasma CDMO was associated with higher glucose and TG levels and HOMA-IR in the OLA-treated patients with schizophrenia." (PMID 35800023, 2022). "Similar to schizophrenia patients, CRP levels were elevated in the present study in both FEMD and RMD patients with small effect sizes." (PMID 35379263, 2022). "For example, a very high level of circulating C-reactive protein (CRP) in schizophrenia patients has been observed." (PMID 35269766, 2022). "Several cytokines such as interleukin 1β, interleukin 6, and C-reactive protein were higher in individuals with schizophrenia." (PMID 35845458, 2022). "The levels of both IKKβ and NIK transcripts, which were specifically lower in high inflammation schizophrenia, were also inversely correlated with IL-1β mRNA and plasma CRP levels in patients." (PMID 35027554, 2022). "Plasma leptin, HOMA-IR and hs-CRP levels should be measured regularly in CS patients to prevent or treat the disorders of glucose and lipid metabolism comorbidity with schizophrenia patients in clinical diagnosis and treatment." (PMID 36090349, 2022). "The conducted studies will respond to the question of whether the development of schizophrenia is associated with an increased level of oxidative stress and whether there is an ROS relationship with an increase in inflammatory markers, such as the CRP reactive protein (CRP)." (PMID 35566680, 2022). "Our findings further contribute to the accumulation of data on the possible role of the inflammation in the development of cognitive impairment in schizophrenia, confirming the CRP as the most promising biomarker among examined." (PMID 35873262, 2022). "A systematic review of cytokines and CRP alterations with respect to cognitive impairment in schizophrenia summarized that most consistent results indicate worse cognitive performance in schizophrenia patients with higher CRP levels." (PMID 35873262, 2022). "We then assessed the relationships between the alterations in NF-κB pathway genes, pro-inflammatory cytokine and CRP levels, psychiatric symptoms and cognition in people with schizophrenia." (PMID 35027554, 2022). "CRP levels were found to be higher in persons with schizophrenia in previous studies, and they were connected to illness severity and recurrence (; L.)." (PMID 35502339, 2022). "Our results are in line with meta-analytical data, which consistently shows increased levels of CRP and IL-6 in schizophrenia." (PMID 36362580, 2022). "C-reactive protein levels were positively correlated with positive-symptom scores in schizophrenia group patients (r Spearman = 0.491, p < 0.05)." (PMID 35566680, 2022). "Some particular mention needs to be made on schizophrenia, where, among the tentative MR findings described in this review we found several studies of CRP and schizophrenia onset." (PMID 32978716, 2021). "C-reactive protein (CRP) levels have also been reported to be elevated in patients with schizophrenia." (PMID 34393855, 2021). "Meta-analyses of CRP levels in schizophrenia, which included a total of 26 cross-sectional or longitudinal studies evaluating 85,000 participants demonstrated that CRP levels were moderately increased." (PMID 34393855, 2021). "Numerous studies have evaluated levels of CRP as a means of identifying inflammatory subgroups in schizophrenia, mostly reporting modestly but significantly elevated levels mainly related to the severity of symptoms occurring during the relapsing phase." (PMID 34702245, 2021).
schizophrenia (continued). "The aim of this study was to assess the level of inflammatory markers high sensitive C-reactive protein (hsCRP) and interleukin-6 (IL-6) in patients with schizophrenia." (PMID 34465310, 2021). "It found baseline CRP levels in individuals with schizophrenia were 63% higher compared to healthy individuals." (PMID 34884840, 2021). "Along with CRP, some studies have shown higher levels of baseline neutrophils and other innate immunological markers in schizophrenia." (PMID 34884840, 2021). "People who have both schizophrenia and high circulating CRP have more severe symptoms (psychiatric and cognitive) and reduced PFC thickness compared to low CRP patients." (PMID 34650030, 2021). "Meta-analyses of cross-sectional studies reported that circulating CRP levels are higher in schizophrenia compared to healthy controls, with medium to large effect sizes." (PMID 34050185, 2021). "The association between CRP and central obesity and infections further complicates interpretation of CRP in the context of schizophrenia." (PMID 34702245, 2021). "Several researchers have attempted to stratify people with schizophrenia based on their immune status in the blood using either pro-inflammatory cytokine transcripts or CRP levels." (PMID 34650030, 2021). "The use of a simple and commonly used biomarker like CRP in assessing schizophrenia has the potential to make an enormous difference in the attitude towards psychotic disorders in resource-strained settings like in healthcare systems of LMICs." (PMID 34884840, 2021). "A number of meta-analyses have reported that patients with schizophrenia and related psychotic disorders have higher CRP levels compared to controls." (PMID 34050185, 2021). "It is imperative that more studies are conducted on larger population cohorts to assess more than just the difference of CRP levels between individuals with schizophrenia and healthy controls." (PMID 34884840, 2021). "Further studies on CRP will invariably allow for alteration in our therapeutic approach to schizophrenia by validating the addition of an anti-inflammatory agent in the regimen." (PMID 34884840, 2021). "More recently, elevations in inflammatory markers including pro-inflammatory cytokines, the acute phase protein CRP, the immune regulator S100B and soluble intracellular cell adhesion molecule have been found in the blood of people with schizophrenia." (PMID 34650030, 2021). "Further evidence from various geographical subgroups linking CRP levels with schizophrenia has strengthened the notion that there is an immune component in active and latent psychosis." (PMID 34884840, 2021). "As a commonly tested biomarker, CRP can have a groundbreaking impact on the diagnosis, management, and prevention of schizophrenia." (PMID 34884840, 2021). "Elevated levels of ICAM-1, VCAM-1, CRP and SAA have been associated with coronary artery disease, cancer and psychiatric disorders including schizophrenia." (PMID 33602170, 2021). "Another study analyzed baseline CRP levels and prevalence of schizophrenia (with possible hospitalization) in 78,810 Danish males." (PMID 34884840, 2021). "A meta-analysis reported higher CRP values in patients with schizophrenia compared to that of the control group." (PMID 34465310, 2021). "MR studies have reported potential causal associations between inflammation, particularly C-reactive protein (CRP) and interleukin-6 (IL-6), and schizophrenia." (PMID 33711016, 2021). "CRP remained unchanged following treatment in schizophrenia (g: 0.28; CI −0.24 to 0.81; p = 0.294; I2 = 76%) and in MDD (g: −0.14; CI −0.87 to 0.59; p = 0.705; I2 = 58%)." (PMID 33653423, 2021). "A large meta-analysis consisting of 85,000 subjects also found a modest rise in CRP levels in patients with schizophrenia." (PMID 34884840, 2021). "We found some evidence for the association of childhood CRP levels with both PRS-T2DM and PRS-schizophrenia." (PMID 32828613, 2020).
schizophrenia (continued). "Hs-CRP appears as a potentially good biomarker, but further studies should confirm if peripheral CRP is a good marker of central neuro-inflammation in schizophrenia, as suggested in one study in depression." (PMID 32256401, 2020). "The lack of any association, in contrast to significant associations of maternal CRP with ASD and schizophrenia suggests different pathways linking maternal immune activation and development of various neuropsychiatric disorders." (PMID 31312974, 2020). "Inflammatory markers such as CRP have been elevated in patients with deficit schizophrenia, which is a term used to describe patients who suffer mostly primary and enduring negative symptoms despite attempts to optimize medication interventions." (PMID 32153436, 2020). "In the schizophrenia group, the inclusion of covariates showed that higher CRP baseline level was related to lower baseline level in global cognitive performance (b=−0.26, p=0.036)." (PMID 30394240, 2019). "Low-grade elevation of the CRP, a well characterised and standardised marker of inflammation, has been found in some studies in schizophrenia." (PMID 30394240, 2019). "CRP levels in schizophrenia also show an inverse correlation with fractional anisotropy within the forceps major." (PMID 29743584, 2019). "Previous studies on patients with schizophrenia have shown an association between increased PANSS-EC and the inflammatory marker CRP." (PMID 31509578, 2019). "Within this context, the possible relationship between a psychotic breakdown evolving in schizophrenia and inflammation proteins, such C-reactive protein (CRP), has been investigated." (PMID 30678202, 2019). "So how do we reconcile this contrast between genetic and observational epidemiological findings regarding the potential role of CRP/inflammation in the pathogenesis of schizophrenia?" (PMID 31563954, 2019). "Paired t-tests revealed a significant difference in working memory (WAIS-III Arithmetic) remained between the patients with schizophrenia displaying normal and elevated CRP who were matched on BMI." (PMID 30364161, 2018). "The chronically ill patients with schizophrenia who displayed elevated CRP had significantly worse working memory performance." (PMID 30364161, 2018). "In our recent study, we reported that Syncytin-1 exhibited a positive correlation and marked consistency with the expression levels of CRP in individuals with schizophrenia." (PMID 30245643, 2018). "Next, in Study 2 (below) we tested the relationship of CRP to symptoms, cognition and brain cortical thickness in a chronically ill sample of people with schizophrenia." (PMID 30364161, 2018). "Extreme outliers (≥ ± 2 standard deviations from the mean) for the CRP variable were excluded from the analysis (total excluded n = 10, schizophrenia group n = 9, healthy control group n = 1)." (PMID 30364161, 2018). "The increase in CRP correlated with positive symptoms of schizophrenia but was unresponsive to initiation of antipsychotic treatment." (PMID 30766494, 2018). "The current work represents our first assessment of CRP as an assay of immune system function in schizophrenia and the degree to which cognitive, symptom, daily function, and brain volume variables differ in relation to CRP in this sample." (PMID 30364161, 2018). "In the current study, the elevated CRP schizophrenia group displayed significantly worse performance on a measure of working memory compared to the normal CRP schizophrenia group after matching for BMI." (PMID 30364161, 2018). "Comparison of demographic, clinical, cognitive, symptom severity, negative emotional states, daily function and quality of life measures between normal and elevated CRP groups in patients with schizophrenia." (PMID 30364161, 2018). "In our study of chronically ill patients with schizophrenia, we showed that CRP was also significantly elevated relative to healthy controls." (PMID 30364161, 2018).
schizophrenia (continued). "Forty three percent of people with schizophrenia had CRP ≥ 3 mg/L (n = 33; CRP range 3.0–12.3) compared to 20% of healthy controls with CRP ≥ 3 mg/L (n = 14; CRP range 3.0–13.5)." (PMID 30364161, 2018). "Our study is the first to assess brain cortical thickness measures in relation to CRP levels in patients with schizophrenia and healthy controls." (PMID 30364161, 2018). "A larger proportion of individuals (~60%) with acute psychosis had elevated levels of CRP, compared to ~44% of the chronically ill patients with schizophrenia." (PMID 30364161, 2018). "Comparison of current IQ and working memory measures between normal and elevated CRP schizophrenia groups matched on BMI." (PMID 30364161, 2018). "Our results suggest that measuring CRP levels in blood of chronically ill people with schizophrenia would also be an indicator of impaired prefrontal cortex function." (PMID 30364161, 2018). "Some healthy controls also displayed elevated CRP, although the proportion (20%) was significantly lower than the proportions displaying elevated CRP in chronically ill patients with schizophrenia and those patients admitted for an acute psychotic episode." (PMID 30364161, 2018). "While we did find some reduction of inflammation across admissions, we saw continued significantly increased CRP in these readmitted patients and a lower, but still significant CRP elevation in chronically ill patients with schizophrenia." (PMID 30364161, 2018). "As predicted, the patients with schizophrenia had significantly elevated CRP levels relative to controls (an 88.9% increase)." (PMID 30364161, 2018). "Studies exploring relationships between C-reactive protein (CRP) blood levels and schizophrenia (SZ): designs and major findings." (PMID 30190688, 2018). "CRP and the pro-inflammatory cytokines are the proteins that at present should be further validated as biomarkers for inflammation in schizophrenia." (PMID 30766494, 2018). "C-reactive protein (CRP), another pro-inflammatory molecule, has recently been found to be sufficiently increased in patients with schizophrenia." (PMID 30245643, 2018). "CRP was significantly elevated in 43% of chronically ill patients with schizophrenia compared to 20% in controls." (PMID 30364161, 2018). "The individuals with schizophrenia had significantly increased odds of having elevated levels of CRP relative to both the 75th and 90th percentile levels of the controls after adjustment for age, gender, race, maternal education, smoking status, and BMI." (PMID 30190688, 2018). "Studies show elevated cytokine and C-reactive protein (CRP) levels, indicating inflammatory markers as potential biomarkers for schizophrenia." (PMID 29434554, 2018). "Three studies found that patients with schizophrenia and higher levels of serum CRP scored higher on psychotic symptom severity rating scales in comparison to those patients with lower serum CRP levels." (PMID 29404313, 2017). "CRP levels were determined in patients with chronic schizophrenia treated with different types of antipsychotics and switched to olanzapine treatment." (PMID 28358316, 2017). "We report a longitudinal study of serum C-reactive protein (CRP) in adolescence and subsequent risk of schizophrenia and related psychoses in adulthood in the Northern Finland Birth Cohort 1986." (PMID 27622678, 2017). "CRP, as an acute-phase marker of inflammation, is found in higher concentrations in patients with schizophrenia than in healthy control subjects." (PMID 28358316, 2017). "Using CRP as a categorical variable according to the AHA/CDC definitions, there were more cases of schizophrenia in the group with high CRP at baseline compared with the group with low CRP." (PMID 27622678, 2017). "The adjusted OR for schizophrenia by age 27 years for each standard deviation (SD) increase in CRP levels at age 15/16 years was 1.25 (95% CI, 1.07–1.46), which was consistent with a linear, dose-response relationship (P-value for quadratic term 0.23)." (PMID 27622678, 2017).